TERB2 (telomere repeat binding bouquet formation protein 2)
Description:
Meiosis-specific telomere-associated protein involved in meiotic telomere attachment to the nucleus inner membrane, a crucial step for homologous pairing and synapsis. Component of the MAJIN-TERB1-TERB2 complex, which promotes telomere cap exchange by mediating attachment of telomeric DNA to the inner nuclear membrane and replacement of the protective cap of telomeric chromosomes: in early meiosis, the MAJIN-TERB1-TERB2 complex associates with telomeric DNA and the shelterin/telosome complex. During prophase, the complex matures and promotes release of the shelterin/telosome complex from telomeric DNA.
Synonyms: C15orf43; MGC33951; SPGF59
Tractability: No criterion of Open Targets' tractability assessment is met for any kind of drug.
Gene: Protein-coding gene on chromosome 15 (44,956,687 to 44,979,229, forward strand). Ensembl gene ENSG00000167014.
Subcellular location: Chromosome, telomere; Nucleus inner membrane
Subcellular location (Human Protein Atlas): Nucleoli; Nucleoplasm
Gene Ontology:
Molecular function: protein binding
Biological process: homologous chromosome pairing at meiosis; meiotic attachment of telomere to nuclear envelope; meiotic telomere clustering
Cellular component: nuclear envelope; nuclear membrane; chromosome, telomeric region; nuclear inner membrane
Genetic constraint (gnomAD): Loss-of-function variants: 15 observed, 21.21 expected, observed/expected ratio (o/e) 0.71, 90% interval 0.47 to 1.09. The upper end of that interval is the gene's LOEUF score, 1.09, which puts it in group 4 of 6, group 1 being the genes least tolerant of losing a copy. Missense variants: 203 observed, 211.59 expected, observed/expected ratio (o/e) 0.96, 90% interval 0.86 to 1.08. Synonymous variants: 73 observed, 74.44 expected, observed/expected ratio (o/e) 0.98, 90% interval 0.81 to 1.19.
Homologues: Orthologues: macaque TERB2 (95% identical), pig TERB2 (94% identical), dog TERB2 (90% identical), rabbit TERB2 (88% identical), guinea pig TERB2 (86% identical), mouse Terb2 (78% identical), rat Terb2 (77% identical), chimpanzee TERB2 (52% identical), zebrafish si:dkey-1h4.5 (35% identical).
Diseases named in the same sentence as TERB2 in open-access papers:
TERB2 is named in the same sentence as 3 diseases in open-access papers, as found by Europe PMC text mining. Sharing a sentence is not in itself a finding about the gene and the disease. The quoted sentences say what the papers report.
Infertility (2 papers, 2019 to 2022). "Likewise, mice disrupted for either MAJIN or TERB2 display impaired synapsis, zygotene arrest, a lack of post-meiotic cells, and infertility phenotype as revealed by Salas-Huetos." (PMID 35342767, 2022).
male infertility (2 papers, 2022 to 2023). The inability of the male to effect fertilization of an ovum after a specified period of unprotected intercourse. "A Terb2 mutation in mice shows defects in the meiotic process and ultimately male infertility." (PMID 37174664, 2023). "The main goal of this work was exploring the effects of missense mutations on meiotic telomere complex proteins (TERB1, TERB2, and MAJIN) related to male infertility." (PMID 35342767, 2022). "Furthermore, disruption or mutations of any of the MTC genes (TERB1, TERB2, and MAJIN) alters telomere association with the nuclear envelope leading to impairment of homologous pairing and synapsis, a meiotic arrest, and consequently to male infertility." (PMID 35342767, 2022).
TERB2 also shares sentences with these, for which no sentence is quoted: spermatogenic failure 59 (1 paper).